NEUROG3 (neurogenin 3)
Description:
Is a transcriptional regulator involved in the control of enteroendocrine cell differentiation. Together with NKX2-2, initiates transcriptional activation of NEUROD1. Involved in neurogenesis. Also required for the specification of a common precursor of the 4 pancreatic endocrine cell types (By similarity).
Synonyms: NGN-3; bHLHa7; ATOH5; NGN3; Math4B
Tractability: No criterion of Open Targets' tractability assessment is met for any kind of drug.
Gene: Protein-coding gene on chromosome 10 (69,571,485 to 69,573,511, reverse strand). Ensembl gene ENSG00000122859.
Subcellular location: Nucleus
Subcellular location (Human Protein Atlas): Nuclear speckles; Nucleoplasm
Pathways (Reactome):
Developmental Biology: Regulation of gene expression in endocrine-committed (NEUROG3+) progenitor cells; Regulation of gene expression in late stage (branching morphogenesis) pancreatic bud precursor cells
Gene Ontology:
Molecular function: DNA-binding transcription repressor activity, RNA polymerase II-specific; protein binding; RNA polymerase II cis-regulatory region sequence-specific DNA binding; chromatin DNA binding; DNA-binding transcription activator activity, RNA polymerase II-specific; DNA-binding transcription factor activity, RNA polymerase II-specific; E-box binding; DNA-binding transcription factor activity; double-stranded DNA binding; protein dimerization activity
Biological process: enteroendocrine cell differentiation; negative regulation of transcription by RNA polymerase II; positive regulation of transcription by RNA polymerase II; axon development; central nervous system development; nervous system development; peripheral nervous system development; positive regulation of DNA-templated transcription; sensory organ development; transdifferentiation; forebrain development; hindbrain development; positive regulation of cell differentiation; positive regulation of neuron differentiation; regulation of DNA-templated transcription; spinal cord development
Cellular component: nucleus; chromatin
Genetic constraint (gnomAD): Loss-of-function variants: 0 observed, 0.0749 expected, observed/expected ratio (o/e) 0, 90% interval 0 to 1.89. That is too few expected variants to judge how well the gene tolerates losing a copy. Missense variants: 288 observed, 291.56 expected, observed/expected ratio (o/e) 0.99, 90% interval 0.9 to 1.09. Synonymous variants: 152 observed, 136 expected, observed/expected ratio (o/e) 1.12, 90% interval 0.98 to 1.28.
Homologues: Orthologues: chimpanzee NEUROG3 (99% identical), macaque NEUROG3 (93% identical), dog NEUROG3 (85% identical), pig NEUROG3 (85% identical), rat Neurog3 (78% identical), mouse Neurog3 (76% identical), tropical clawed frog neurog3 (45% identical), zebrafish neurog3 (36% identical), Drosophila melanogaster tap (31% identical), Caenorhabditis elegans ngn-1 (25% identical), Drosophila melanogaster ato (19% identical), Caenorhabditis elegans lin-32 (15% identical), and 1 more. Paralogues in human: NEUROG1 (39% identical), NEUROG2 (39% identical), NEUROD1 (29% identical), NEUROD2 (28% identical), NEUROD6 (28% identical), NEUROD4 (27% identical), ATOH1 (22% identical), ATOH8 (21% identical), BHLHE23 (21% identical), BHLHE22 (20% identical), BHLHA15 (20% identical), ATOH7 (19% identical), and 3 more.
Diseases named in the same sentence as NEUROG3 in open-access papers:
NEUROG3 is named in the same sentence as 51 diseases in open-access papers, as found by Europe PMC text mining. Sharing a sentence is not in itself a finding about the gene and the disease. The quoted sentences say what the papers report.
diabetes (46 papers, 2007 to 2025). "Fourth, the Neurog3+ progenitors that are exposed to maternal overnutrition, an established risk factor for diabetes, express lower levels of DNMT3a and Myt1." (PMID 38496675, 2024). "Biallelic mutations in NEUROG3 are known to cause early-onset malabsorptive diarrhea due to congenital anendocrinosis and diabetes mellitus at a variable age." (PMID 27533310, 2016). "In addition, a study involving 31 Chinese families with diabetes revealed 32 mutations across six genes including NEUROG3, which was a novel causative gene for MODY." (PMID 41614819, 2025). "Patients with neurogenin 3 deficiency show congenital diarrhea and diabetes." (PMID 27533310, 2016). "Nonetheless, it is evident that NEUROG3 is of great importance for beta cell development and function as all biallelic mutated patients present with permanent diabetes, although the threshold level of NEUROG3 requirement may be relatively low since all heterozygous parents are not diabetic." (PMID 29096722, 2017). "The efficiency of inducing human embryonic stem cells into NEUROG3+ pancreatic endocrine cells is a bottleneck in stem cell therapy for diabetes." (PMID 37098639, 2023). "HNF1B is important during pancreas development where its mutation causes monogenic diabetes in humans, and functions upstream of SOX9 and NEUROG3 reflecting its late regulatory role during PP development." (PMID 36749553, 2023). "Because of the central role of NEUROG3 in endocrine differentiation, understanding the regulatory network of NEUROG3, as well as the molecular characteristics of NEUROG3+ cells in humans, has large implications for diabetes treatment." (PMID 34566896, 2021). "Because diabetes is mostly diagnosed in adults, understanding the signatures of NEUROG3+ cells in the post-developmental human pancreas is important from the point of diabetes treatment." (PMID 34566896, 2021). "We conclude that postnatal NEUROG3+ cells are likely resident endocrine progenitors that can be further functionally and bioinformatics explored to gain insights on diabetes therapies." (PMID 34566896, 2021). "For example, cluster 5, which is enriched in genes involved in mature onset diabetes of the young, contains tags with peak expression in the Neurog3 EGFP+ libraries and genes in this cluster predominately show pan-epithelial or trunk expression." (PMID 18554416, 2008). "Neurog3 gene knockout mice have no islet endocrine cells, and in humans, known NEUROG3 mutations contribute to diabetes development to varying degrees." (PMID 39045459, 2024). "The gene NEUROG3 is essential in EEC differentiation, and mutations in this gene lead to a paucity of EEC in the intestine and pancreas, often presenting clinically as congenital diarrhea and diabetes mellitus." (PMID 37168762, 2022). "Neurog3 deficient mice do not have any pancreatic endocrine cells, develop diabetes, and die shortly after birth." (PMID 34566896, 2021). "As NEUROG3 plays a central role in endocrine differentiation, knowledge gained from our study will accelerate the development of beta cell regeneration therapies to treat diabetes." (PMID 34566896, 2021). "Neurog3 is another well-studied transcription factor, in part due to the dramatic phenotype of Neurog3-deficient mice, comprising a total lack of pancreatic endocrine cells, neonatal diabetes and early postnatal death." (PMID 32894307, 2020). "Reconciliation in the field, however, was short lived as, more recently, two individuals with biallelic functionally null variants of the NEUROG3 gene without permanent neonatal diabetes mellitus were reported." (PMID 32894307, 2020). "Unexpectedly, these individuals did not have permanent neonatal diabetes mellitus, despite their severe NEUROG3 mutations, suggesting that an unidentified factor compensated for the lack of functional NEUROG3 in the human pancreas." (PMID 32894307, 2020).
diabetes (continued). "Biallelic mutations in NEUROG3 are known to cause a rare but well-defined clinical syndrome characterized by severe malabsorptive diarrhea from early life and mild nonketotic diabetes with a variable age of onset." (PMID 27533310, 2016). "Unfortunately, because b cells re-activate Neurog3 under metabolic stress during diabetes development, which we expect to label M−N+ progenitor-derived b cells after birth, we could not compare the function of the adult b-cell subtypes from M−N+ and M−N+ progenitors in the maternal HFD model." (PMID 38496675, 2024). "However, NEUROG3 homozygous loss-of-function mutations have been reported due to abnormal entero-endocrine differentiation, with variable degrees of severity of signs and symptoms and the potential onset of PNDM or pediatric diabetes." (PMID 34584998, 2021). "Based on these findings, we suggest that ductal cells could represent a renewable source of new β-like cells and that strategies aiming at controlling the expression of Neurog3, or of its molecular targets/co-factors, may pave new avenues for the improved treatments of diabetes." (PMID 30092080, 2018). "Conversely, in NEUROG3-deficient mice, four islet cell types (alpha, beta, delta, and pancreatic polypeptide cells) and endocrine precursor cells are not generated, and neonates die postnatally from diabetes." (PMID 29096722, 2017). "Biallelic mutations in NEUROG3 result in severe congenital malabsorptive diarrhea due to a lack of enteroendocrine cells in the gut and diabetes with a variable age of onset, in keeping with the role of neurogenin 3 in pancreatic endocrine differentiation during embryonic development (1, –, 3)." (PMID 27533310, 2016). "In the “Maturity onset diabetes of the young” pathway, the upregulation of HHEX and downregulation of HES1 could increase the expression of NEUROG3 and outcomes such as the Insulin signaling pathway." (PMID 36835058, 2023). "Thus, although Myt1 co-expression with Neurog3 during embryogenesis represents the progenitors of better-function cells, this model is not fit for studying b-cell subtype stability in diabetes-prone models at postnatal stages." (PMID 38496675, 2024). "Other attempts to deliver combinations of transcription factors, such as Pdx1 and Neurogenin 3 (Ngn3), improved the blood glucose levels of diabetic mice, but could not fully cure diabetes." (PMID 33023100, 2020). "Importantly, no upregulation of progenitor markers, such as neurogenin 3 (NEUROG3), POU class 5 homeobox 1 (POU5F1), and nanog homeobox (NANOG) was found in T2D β-cells, in contrast to what was previously reported in diabetes mouse models." (PMID 38731945, 2024).
Hyperglycemia (19 papers, 2012 to 2025). An increased concentration of glucose in the blood. "Consequently, the NEUROG3 gene is associated with hyperglycemia." (PMID 41614819, 2025). "This seems to conflict with our finding that an endocrine progenitor-specific miR-7 gene family knockout using a Neurog3-Cre driver leads to reduced β-cell mass and adult-onset hyperglycemia." (PMID 39055950, 2024). "Hyperglycemia inhibits nuclear translocation and expression of forkhead box-O1 (FoxO1) and induces the expression of neurogenin-3 (Ngn3), which is required for the development and maintenance of pancreatic endocrine progenitor cells." (PMID 33918379, 2021). "In this regard, a direct contribution of an altered expression of transcription factors involved in the maintenance of β-cell identity (e.g. PDX1, NKX6.1, MAFA or NEUROG3, among others) has been proposed to explain β-cell failure under pathological conditions of hyperglycemia and lipotoxicity." (PMID 37274331, 2023). "Interestingly, despite a previous report indicating that mice expressing Neurog3 under the control of the insulin promoter would die shortly after birth due to hyperglycemia, InsCre::Neurog3OE double transgenics were viable, fertile, healthy, and displayed normal basal glycemia (data not shown)." (PMID 30092080, 2018). "Together, our results indicate that the maintained expression of Neurog3 in neogenerated β-like cells does not alter their function, such cells secreting insulin and being able to counter the consequences of glucose-induced hyperglycemia." (PMID 30092080, 2018).
type 2 diabetes (7 papers, 2013 to 2025). "Among the hub genes screened, four genes (NEUROG3, TCF7L2, MAP2K5 and RPTOR) were validated as showing the upregulated expression pattern in blood samples in type 2 diabetes cases." (PMID 34830198, 2021).
Obesity (6 papers, 2013 to 2023). Accumulation of substantial excess body fat. "Here, we demonstrate that early embryonic hypothalamic inactivation of Ngn3 (also known as Neurog3) in mice results in rapid post-weaning obesity that is associated with hyperphagia and reduced energy expenditure." (PMID 23649822, 2013). "The model was generated by hypothalamic deletion of Ngn3 (also known as Neurog3), which results in rapid post-weaning obesity, concomitant with increased food intake (hyperphagia) and reduced energy expenditure." (PMID 23649822, 2013). "Interestingly, rats with diet-induced obesity in the pair-fed group maintained high levels of Pdx1 and Neurog3, pointing to an increased formation of insulin-secreting β-cells." (PMID 37274331, 2023). "The pancreata of rats with diet-induced obesity showed a high expression of Pdx1 (P<0.05) together with low transcript levels of Wnt4 (P<0.05), without changes in Neurog3." (PMID 37274331, 2023).
pancreatic cancer (6 papers, 2017 to 2025). "NeuroD1 and Neurog3 induce the transdifferentiation of pancreatic cancer cells into cells with neuron-like phenotypes." (PMID 41225636, 2025). "In summary, our findings indicate that NeuroD1 interacts with Neurog3, and suppresses the proliferation of pancreatic cancer cells both in vitro and in vivo." (PMID 41225636, 2025). "The proportion of cells expressing neuronal markers was also significantly increased, indicating that Neurog3 induces the phenotypic transformation of pancreatic cancer cells into neuron-like cells." (PMID 41225636, 2025). "And the rescue experiments confirmed that Neurog3 is indispensable for the transdifferentiation of pancreatic cancer cells." (PMID 41225636, 2025). "The results showed that Neurog3 overexpression markedly reduced the proliferative capacity of pancreatic cancer cells while significantly increasing apoptosis of the cells." (PMID 41225636, 2025). "Consistent with this, IF staining for Map2 and Tuj1 in Neurog3-overexpressing cells revealed that Neurog3 upregulated the transdifferentiation of pancreatic cancer cells into cells with neuron-like phenotypes." (PMID 41225636, 2025). "We established subcutaneous tumor models in mice using Panc-1 and SW1990 cells and used these models to investigate the effects of Neurog3 overexpression on the progression of pancreatic cancer in vivo." (PMID 41225636, 2025). "In contrast, our findings revealed that the role of NeuroD1 in pancreatic cancer is mediated through Neurog3." (PMID 41225636, 2025). "We found that Neurog3 overexpression significantly inhibited both the proliferation and the migration of pancreatic cancer cells." (PMID 41225636, 2025). "We found that Neurog3 overexpression significantly inhibited the in vivo progression of pancreatic cancer." (PMID 41225636, 2025). "However, in terms of inductive efficacy, NeuroD1 exhibits a significantly higher capacity than Neurog3 to induce pancreatic cancer cells to transdifferentiate into neuron-like phenotypes." (PMID 41225636, 2025). "IF staining for Map2 and Tuj1 revealed that in pancreatic cancer cells with low NeuroD1 expression, neither the control nor Neurog3-knockdown groups exhibited transition to a neuron-like phenotype, whereas Neurog3 overexpression partially induced this transition." (PMID 41225636, 2025). "IPF1/PDX1 regulates downstream molecules such as Neurogenin 3 (NGN3), Forkhead Box A2 (FOXA2), Hepatocyte Nuclear Factor 1 Beta (HNF1B), Fibroblast Growth Factor Receptor 2 (FGFR2IIIB), and Spondin 1, which are involved in pancreatic development, differentiation, and function in pancreatic cancer." (PMID 39239563, 2024).
type 1 diabetes (6 papers, 2017 to 2024). "In human type 1 diabetes pancreatic islets, fasting conditions reduce PKA and mTOR activity and induce Sox2 and Ngn3 (Neurogenin 3) expression and insulin production." (PMID 29480368, 2018).
Atrophy (3 papers, 2007 to 2022). Any weakening or degeneration, especially through lack of use. "It was involved in the loss of neurogenin-3 (Ngn3)-positive endocrine progenitor cells, pancreatic atrophy, and reduced insulin sensitivity to endogenous glucose production leading to the reduction of insulin secretion." (PMID 35480487, 2022). "It was involved in the loss of neurogenin-3 (Ngn3)-positive endocrine progenitor cells, pancreatic atrophy, and a reduced insulin sensitivity to endogenous glucose production leading to the reduction of insulin secretion." (PMID 32329795, 2020).
Infertility (2 papers, 2012 to 2025). "Deletion of Dicer1 in type A spermatogonia by Neurog3 promoter-driven cre (Ngn3-cre) resulted in defective spermatogenesis and infertility characterized by the arrest of spermatid elongation prior to the histone-protamine exchange." (PMID 23056286, 2012).
maturity-onset diabetes of the young (2 papers, 2024 to 2025). "Additionally, we observed both up- and downregulation of genes related to maturity onset diabetes of the young (MODY) in VAT and SAT, respectively, such as hepatocyte nuclear factor (HNF) genes and Neurogenin 3 (NEUROG3; also see Suppl." (PMID 39333229, 2024).
pancreatic ductal adenocarcinoma (2 papers, 2017 to 2022). An infiltrating adenocarcinoma that arises from the epithelial cells of the pancreas. "Furthermore, in murine pancreatic ductal adenocarcinoma cells, it was shown that Atoh8 with the help of its proline-rich domain represses Neurog3-mediated gene function by competing with the transcriptional activity of E47 and Neurog3." (PMID 35053134, 2022).
Chronic diarrhea (1 paper, 2020). The presence of chronic diarrhea, which is usually taken to mean diarrhea that has persisted for over 4 weeks. "In addition, human enteroendocrine cell deficiency as well as mutations in enteroendocrine gene NEUROG3 have been linked to chronic diarrhea and malabsorption, and recently, intestinal enteroendocrine cells have been suggested to play a role in mediating intestinal immune tolerance." (PMID 32410729, 2020).
Constipation (1 paper, 2017). Infrequent or difficult evacuation of feces. "The densities of Msi-1, NEUROG3, CgA, and serotonin cells were reduced in all IBS patients and in patients with diarrhea-predominant IBS (IBS-D), mixed-diarrhea-and-constipation IBS (IBS-M), and constipation-predominant (IBS-C) relative to the control subjects." (PMID 28764761, 2017).
hypogonadotropic hypogonadism (1 paper, 2016). Abnormal ovarian or testicular function due to insufficient hormonal stimulation from the hypothalamic-pituitary axis. "The novel and consistent association of persistent hypogonadotropic hypogonadism in these patients suggests that the expression of NEUROG3 in the hypothalamus also plays an unexpected role in postnatal pubertal development." (PMID 27533310, 2016). "We describe four patients with two different homozygous mutations in NEUROG3 who have hypogonadotropic hypogonadism and short stature, and we elaborate on the potential mechanisms underlying these associations." (PMID 27533310, 2016). "NEUROG3 mutations expand on the growing number of genetic causes of acquired hypogonadotropic hypogonadism." (PMID 27533310, 2016).
latent infection (1 paper, 2025). "To develop an in vitro human neuronal cell culture model for latent infection with HSV-1, we used human neurogenin 3 (NEUROG3) iPSC (iNGN3) derived from Personal Genome Project Participant 1 iPSCs." (PMID 40823836, 2025).
malnutrition (1 paper, 2013). Inadequate nutrition resulting from poor diet, malabsorption, or abnormal nutrient distribution. "An intestine-specific deletion of Ngn3 (also known as Neurog3) in mice results in a failure to produce a number of gut enzymes, including those involved in lipid metabolism, resulting in a lean phenotype and death in early adulthood from malnutrition." (PMID 23649822, 2013).
Stroke (1 paper, 2025). Sudden impairment of blood flow to a part of the brain due to occlusion or rupture of an artery to the brain. "HTR3D and NEUROG3 were linked with the susceptibility of PSD and PIK3C2B with stroke in the Chinese Han population." (PMID 40529498, 2025).